BECN1 (beclin 1)
Diseases named in the same sentence as BECN1 in open-access papers (continued):
Sharing a sentence is not in itself a finding about the gene and the disease.
Sepsis (continued). "In this study, mouse models of lipopolysaccharide induced sepsis were used to conduct experiments which suggested that beclin-1-dependent autophagy might protect the heart from sepsis." (PMID 36793476, 2023). "The autophagy level is significantly inhibited in septic patients with acute respiratory distress syndrome, and autophagy-associated proteins LC3II, Beclin-1, RAB7, LAMP2, and p62 have good value for the diagnosis and prognosis evaluation of sepsis comorbid with acute respiratory distress syndrome." (PMID 35371338, 2022). "In our study, experiments revealed that beclin-1 was upregulated in the sepsis group." (PMID 35815056, 2022). "Moreover, the levels of autophagy-related proteins LC3II, Beclin-1, Rab7, Lysosomal Associated Membrane Protein 2 (LAMP2) and p62 had good value in the diagnosis and prognosis of ARDS patients due to sepsis." (PMID 36059534, 2022). "Our evaluation of TB-peptide previously in the endotoxemia model and currently in the pneumonia-induced sepsis model have provided novel evidence supporting the notion that pharmacological approaches targeting Beclin-1 signaling possess important therapeutic values for sepsis." (PMID 34211859, 2021). "In the study summarized in this report, we extended our investigation to examine the potential role of MAMs in the mitochondrial pathology in sepsis and to determine whether Beclin‐1 possesses a regulatory power over this process." (PMID 33733054, 2021). "In this study, we applied both genetic and pharmacological approaches to evaluate whether Beclin-1 activation improves sepsis outcomes in a model of pneumonia-induced sepsis." (PMID 34211859, 2021). "In this investigation, we designed a study to further address whether targeted activation of Beclin-1 possesses therapeutic potential for sepsis using a previously established model of pneumonia-induced sepsis, which has more clinical relevance." (PMID 34211859, 2021). "Whether increasing Beclin-1–dependent autophagy has an effect on the control of overwhelming inflammation induced by pneumonia-induced sepsis was also addressed." (PMID 34211859, 2021). "BNIP3 signaling stimulates pathological responses under conditions of hypoxia and ischemia/reperfusion, however, whether BNIP3 is pathological in sepsis-induced cardiac dysfunction and how Beclin-1 interacts with BNIP3 require further investigation." (PMID 30744190, 2019). "However, the regulatory function of Beclin-1 in various cell types and tissues under the pathological condition of sepsis remain further investigation." (PMID 30744190, 2019). "Statistical analysis was applied according to published methods, and data revealed that activation of Beclin-1 either genetically (Becn1F121A/F121A) or pharmacologically (TB-peptide) significantly reduced the overall sickness scores in response to pneumonia-induced sepsis." (PMID 34211859, 2021). "We previously demonstrated that promoting Beclin-1–dependent autophagy is cardiac protective during endotoxemia shock, suggesting that autophagy-based approaches may become a promising therapeutic strategy for sepsis." (PMID 34211859, 2021). "Additionally, CO activated autophagy through Beclin‐1 in the sepsis mice." (PMID 33963627, 2021). "Activation of Beclin-1 by forced expression of Becn1F121A/F121A or by TB-peptide provided similar levels of substantial reduction in circulating cytokines, as well as in pulmonary cytokines, indicating that Beclin-1–dependent autophagy provides anti-inflammatory effects during sepsis." (PMID 34211859, 2021). "A 2023 literature reported that macrophages inhibit autophagy through NET-mediated EGFR-BECN1 signaling to accelerate inflammatory vesicle activity thereby promoting atherosclerosis formation, and BECN1-dependent autophagy ameliorates lung injury and inflammation in sepsis and may protect the heart." (PMID 38114939, 2023). "Increased LC3-II and BECN1 expression have been found in SI-AKI, indicating the autophagy status enhanced during sepsis." (PMID 37215112, 2023).
Sepsis (continued). "Western blot outcomes revealed that in the peripheral blood monocytes of sepsis sufferers with ARDS, the relative expression levels of LC3II, Beclin-1, RAB7, and LAMP2 were remarkably lower in contrast to the non-ARDS group (P < 0.05)." (PMID 35371338, 2022). "Beclin-1 has been shown to increase in parallel with LC3 II, preserving cardiac mitochondrial integrity during sepsis." (PMID 35740442, 2022). "In rat sepsis model induced by CLP, sepsis induces cardiac Beclin-1 acetylation to inhibit autophagy, resulting in impaired cardiac function." (PMID 36506093, 2022). "Age, CRP, PCT, APACHE II, SOFA, LC3II, Beclin-1, RAB7, LAMP2, and p62 are related to the death of patients with sepsis and ARDS." (PMID 35371338, 2022). "In this study, we found that sepsis induced more double-membrane autophagosomes, the shift from LC3-I to LC3-II, increased levels of beclin-1 and Atg-5, and reduction in free p62 in the mouse hippocampus, indicating the activation of hippocampal autophagy." (PMID 34711216, 2021). "During sepsis, LPS-induced HIF-1α expression upregulates the production of ROS, inflammatory cytokines, and proapoptotic proteins (e.g., caspase-3, BNIP-3, and Beclin-1), contributing to inflammation and apoptosis." (PMID 33567713, 2021). "To determine whether the ability of IRF7 to defend against polymicrobial sepsis is dependent on autophagy, we treated mice that underwent CLP with either BECN1 or Wort." (PMID 41212050, 2025). "This study emphasized the upregulation of autophagy-related proteins, such as LC3, Atg7, and Beclin 1, mediated by ghrelin through AMPK-dependent pathways, which also mitigates mitochondrial dysfunction and oxidative stress, key drivers of sepsis-induced organ damage." (PMID 39857660, 2024). "To explore the effect of XBJ on cardiomyocyte autophagy during sepsis, we measured LC3-II/LC3-I ratio and the expression of the proteins Beclin-1 and P62 by western blot in the myocardium of different groups over the course of five time points (12h, 1d, 2d, 3d and 5d)." (PMID 37219401, 2023). "The expression of LC3II, Beclin-1, RAB7, and LAMP2 in sepsis patients with ARDS was significantly reduced; p62 was significantly increased, which suggests that autophagy was inhibited in patients with sepsis and ARDS." (PMID 35371338, 2022). "We found significant differential expression of LC3B-II, Atg5, and Beclin-1 between WT and Tg mice with or without sepsis." (PMID 27508931, 2016). "The upregulation of LC3B-II, Atg5, and Beclin-1 proteins in the Tg mice without sepsis suggests that IκBβ* affects the expression of Autophagy Related genes (Atgs)." (PMID 27508931, 2016). "Drugs that induce (Tat-Beclin1; BECN1) or inhibit (wortmannin; Wort) autophagy decreased and increased bacterial loads, respectively, in WT mice 16 hours after CLP, suggesting that autophagy is the critical mechanism by which pathogens are eliminated during sepsis." (PMID 41212050, 2025). "Thus, the protection by Beclin-1 during sepsis does not seem to be restricted to the heart." (PMID 30744190, 2019). "Thus, HIPK2-mediated autophagy is likely independent of Beclin-1 in sepsis." (PMID 30154452, 2018). "However, Beclin-1 expression was not changed by sepsis or HIPK2 overexpression." (PMID 30154452, 2018). "In addition, neither HIPK2 overexpression nor sepsis altered the level of the Beclin-1 protein." (PMID 30154452, 2018).
glioblastoma (51 papers, 2008 to 2026). The most malignant astrocytic tumor (WHO grade IV). "In addition, deficiencies in genes regulating autophagy, like beclin-1, the key mediator of autophagy and disturbances in the survival signalling pathways, are linked to glioblastoma development." (PMID 41511337, 2025). "To determine whether CPP-induced autophagy relies on the same initiation molecules, we examined MEF deficient of FIP200 expression and a glioblastoma cell line U251, in which Beclin 1 was constitutively knocked-down." (PMID 23285000, 2012). "Combining CPUK02 with TMZ in U87 glioblastoma cells increased the Beclin-1 expression, suggesting enhanced autophagy initiation." (PMID 41346768, 2026). "ABT-737 and its derivatives (ABT-263 and ABT199) inhibit the interaction between Beclin-1 and Bcl2 to induce autophagic-like cell death, which has anticancer effects on glioblastoma cells." (PMID 40248706, 2025). "As it results from the conducted research, blocking the expression of both beclin 1 and Bcl-2 protein completely eliminated the autophagy in anaplastic astrocytoma and glioblastoma multiforme cells." (PMID 39352533, 2025). "Despite strong preclinical rationale, direct clinical implementation of strategies targeting the Bcl-2:beclin-1 checkpoint in glioblastoma multiforme has been constrained by several practical barriers." (PMID 41511337, 2025). "Simultaneous application of LY294002 and sorafenib in anaplastic astrocytoma, as well as in glioblastoma multiforme, affected the co-localization of Bcl-2 and beclin-1, which were distributed around the formed apoptotic bodies." (PMID 38067099, 2023). "miR-93 was shown to control autophagic activity in GSC glioblastoma stem cells by inhibiting BECN1/Beclin 1, ATG5, ATG4B, and SQSTM1/p62." (PMID 36834933, 2023). "EMT regulators Snail and Slug were upregulated in glioblastoma cells after autophagy inhibition by silencing Beclin-1, leading to enhancement of migration and invasion." (PMID 36313039, 2022). "The mitochondrial damage caused glioblastoma cells to undergo autophagy preferentially by downregulating the expression of PARL and changing the ratio of BECN1/Bcl‐2 and the process of mitophagy was regulated by the PI3K/Akt/MAPK/mTOR/Ulk1 pathway." (PMID 34799992, 2022). "Beclin 1 is a key component of the autophagy initiation complexes in normal and pathological conditions such as glioblastoma." (PMID 33525678, 2021). "Xenograft tumors generated from U87 glioblastoma cells showed that both Beclin 1 depletion, as well as the expression of a Beclin 1 S30A mutant, decreased tumorigenesis, and the reconstitution with wild-type Beclin 1 increased it." (PMID 31877888, 2019). "The aim of our study was to investigate the link between DJ-1 and Beclin-1 in glioblastoma through the immunohistochemical expression of such proteins and to correlate the data obtained with prognosis." (PMID 31434323, 2019). "A study comparing the effects of curcumin and solid lipid curcumin particles on autophagy and mitophagy in glioblastoma multiforme cells showed that SLCPs demonstrated superior induction of autophagy markers (Atg5, Atg7, Beclin-1, and LC3A/B) compared to Cur in U-87MG, GL261, and F98 GBM cell lines." (PMID 40227413, 2025). "In addition, reduction of autophagy-related proteins, including Beclin-1, Atg5, and Atg7, enhanced the migration and invasion of glioblastoma cells with EMT regulators." (PMID 40248706, 2025). "Similarly, HIF2α contributes to glioblastoma progression by regulating genes such as GPx1, vasorin, beclin-1, and galectin-3, thereby influencing the response to oxidative stress, angiogenesis, autophagy, and cell survival." (PMID 38893207, 2024). "The most frequently observed types of PCD in glioblastoma cells are apoptosis (type I) and autophagy (type II), which are regulated at the molecular level by numerous proteins, including Bcl-2 (apoptosis) and beclin-1 (autophagy)." (PMID 38067099, 2023).
glioblastoma (continued). "However, Dcf1 increased BECN1/Bcl‐2 ratio after 24 h, which suggested that Dcf1 preferentially drove glioblastoma cells to undergo autophagy." (PMID 34799992, 2022). "Earlier findings have reported the lower levels of Beclin-1 transcript in glioblastoma." (PMID 33525678, 2021). "Lower levels of Beclin-1 transcript and protein were reported in glioblastoma." (PMID 32707662, 2020). "On the other hand, genetic inhibition of ATG5, ATG7, or Beclin-1 cause augmentation of cell motility and invasiveness along with upregulation of the transcription factors SNAIL and SLUG in glioblastoma cells, indicating that autophagy induction can also be a target to inhibit EMT." (PMID 33233671, 2020). "Probably, the overexpression of other factors, like High Mobility Group A (HMGA) which are general architectural chromatin proteins, that may induce autophagy can influence both the beclin-1 and DJ-1 levels in glioblastoma." (PMID 31434323, 2019). "Integrating new concepts of cell death reprogramming and systems-level signalling analysis, we propose that targeting the Bcl-2:beclin-1 complex and its upstream regulators could overcome the adaptive plasticity of glioblastoma multiforme and open new directions for combination treatment strategies." (PMID 41511337, 2025). "Therefore, after conscientious investigation of the level and type of cell death after single and combined action of LY294002 and sorafenib in anaplastic astrocytoma and glioblastoma multiforme cells, localization changes and co-localization of Bcl-2 and beclin-1 proteins were analyzed." (PMID 38067099, 2023). "Intriguingly, Beclin-1 was reported to induce apoptosis of glioblastoma cells through binding to Bcl-xL, whereas another research suggested that heterooligomers formed by Bcl-xL and Beclin-1 could maintain full anti-apoptotic function in HeLa cells induced by staurosporine." (PMID 34118966, 2021). "Noticeably, tiny iron oxide structures enhance Beclin-1 production, leading to increased ATG5 levels, promoting autophagy-triggered ferroptosis in the treatment of glioblastoma." (PMID 39650649, 2024). "It has been reported that TFEB is overexpressed in glioblastoma, along with other genes that codify for autophagic proteins, such as LC3A, LC3B, Beclin 1, Ulk 1, Ulk 2, p62, and SQSTM1." (PMID 32707662, 2020). "The combined treatment with luteolin (20 μM) and silibinin (50 μM) suppressed the autophagic activity, as demonstrated by the downregulated expression of LC3 I, LC3 II and Beclin 1, and induced the apoptotic process in U87MG and T98G glioblastoma cells." (PMID 32927836, 2020). "Following 24h incubation of lung and glioblastoma cell lines, a substantial accumulation of LC3A, LC3C and of Beclin-1 proteins was evident by confocal microscopy, which was also confirmed on western blot analysis." (PMID 26378792, 2015). "Western blotting showed that Dcf1 inhibited the expression of PARL, and the subcellular colocalization of BECN1‐Bcl‐2 in endoplasmic reticulum (ER) was not changed by Dcf1, suggesting that autophagy and apoptosis occurred in glioblastoma cells simultaneously." (PMID 34799992, 2022). "However, when knockdown of beclin-1 or 3-MA (initial stage autophagic flux inhibitor) were used, the cytotoxic effect of ATO on glioblastomas was avoided." (PMID 33233671, 2020). "To verify the precise effect of altered autophagy in SH-mediated cell death, we investigated the role of RNA interference against Beclin-1 and ATG5 or an autophagy activator (Rapa) and autophagy inhibitors (3-MA, WORT and CQ) in SH-induced glioblastoma cell death." (PMID 28891980, 2017). "Treatment withenglerin A or chloroquine did not result in differences in Beclin-1 levels ineither glioblastoma or renal cancer cells." (PMID 23144724, 2012).
glioblastoma (continued). "Moreover, BBR has been suggested to induce autophagy in glioblastoma by targeting the AMP-activated protein kinase (AMPK)/mechanistic target of rapamycin (mTOR)/ULK1 pathway and in liver cancer cells by stimulating the release of beclin-1 from the Bcl-2/beclin-1 complex." (PMID 35572960, 2022).
ischemia (50 papers, 2012 to 2025). A hypoperfusion of the BLOOD through an organ or tissue caused by a PATHOLOGIC CONSTRICTION or obstruction of its BLOOD VESSELS, or an absence of BLOOD CIRCULATION. "ROS-induced autophagy was demonstrated when HBOT preconditioning upregulated protein expression levels of LC3-II and Beclin 1, causing autophagosomes to form in the ischemic penumbra post-ischemia in rat brain models." (PMID 32899709, 2020). "However, a significant association between Beclin-1 and Vps34 was detected at 30 days, which was supported by the Vps34/Beclin-1 complex formation at 15 and 30 days post-ischemia." (PMID 26042033, 2015). "SP600125 treatment suggests that JNK triggered Beclin-1-induced autophagy and caspase-3-dependent apoptosis during ischemia and tIRI, respectively." (PMID 39408774, 2024). "Ninety minutes after CI, it was determined that the Beclin‐1 protein level and the number of Beclin‐1 positive cells in the ischemia group decreased in the penumbra area when compared to the Control and Sham CI groups (p < 0.05)." (PMID 38520223, 2024). "The GIT1 protein can regulate the level of mitochondrial autophagy during neuronal ischemia-reperfusion by regulating the phosphorylation of Beclin-1 to protect neurons during spinal cord ischemia-reperfusion." (PMID 35340202, 2022). "Because neuronal injury and death primarily occurred 3 days after IR, we focused on the immune expression of Beclin-1 in the infarcted penumbra following ischemia for 60 min and 3 days of reperfusion." (PMID 36171540, 2022). "We have previously shown that the stimulation of autophagy by Tat-Beclin 1 is protective during ischemia and the early phase of reperfusion but is detrimental during the late phase of reperfusion in the heart." (PMID 35053374, 2022). "According to immunostaning results, blebbistatin remarkably reduced Beclin 1 and LC3B fluorescence in neurons caused by ischemia/reperfusion." (PMID 32513915, 2020). "Beclin-1, an autophagy-related gene, was used to explore the effects of COHb on autophagy in ischemia reperfusion injury in the study." (PMID 29137368, 2017). "Due to the degradation of autophagosomes, beclin-1 and p62 were significantly degraded after 1-h ischemia and 3-h reperfusion injury." (PMID 28420993, 2017). "High expression levels of LC3B and Beclin-1 in the MCAO + HCY group suggested that Hcy significantly enhanced ischemia-induced activation of neuronal autophagy." (PMID 27455253, 2016). "To further confirm that Hcy enhanced autophagic activity in the ischemia brain, we analyzed the expression of microtubule-associated protein 1A light chain 3 (LC3B) and Beclin-1 proteins in the ischemic cortex 24 h after brain injury by western blot." (PMID 27455253, 2016). "Dramatic increases of autophagosomes in penumbra neurons have been shown beginning at 6 hours and lasting up to 48 hours post-ischemia in tMCAO rats through upregulation of Beclin-1." (PMID 23675488, 2013). "We found that autophagy was markedly induced with the upregulation of LC3/Beclin 1 and downregulation of p62 in the penumbra at various time intervals following ischemia." (PMID 23029398, 2012). "When autosis is already induced in cardiomyocytes during ischemia/reperfusion, Tat-BECN1 exacerbates myocardial injury; while administration of Tat-BECN1 prior to ischemia/reperfusion or at the time of reperfusion reduces cell death and protects cardiac function." (PMID 36172279, 2022). "Such a different effect of TAT-14-3-3ε on LC3B-II and Beclin-1 may reflect different signal pathways for autophagy in rat ischemia model." (PMID 24671253, 2014). "The western analysis results revealed the ratio of LC3-II/LC3-I and the expression of Beclin 1 increased as early as 1 h after ischemia, augmented significantly at 6 h, peaked at 24 h and lasted for 48 h postischemia (*p<0.05 vs. the Sham group; #p<0.05 vs. I/R-24 h group)." (PMID 23029398, 2012).